FGFR4 (fibroblast growth factor receptor 4)
Diseases named in the same sentence as FGFR4 in open-access papers (continued):
Sharing a sentence is not in itself a finding about the gene and the disease.
breast cancer (continued). "This review explores the structure, signaling pathways, and implications of FGFRs, particularly FGFR1, FGFR2, FGFR3, and FGFR4, in ER+ breast cancer." (PMID 39040443, 2024). "On the other hand, we explored the effect of FGFR4 level on breast cancer outcome and found that high FGFR4 level was correlated with shortened disease‐specific survival, relapse‐free survival, and progress‐free survival of breast cancer." (PMID 39658878, 2024). "The GSEA enrichment evaluation based on the expression of FGFR4 showed that the fatty acid metabolism activity was closely related with breast cancer tumorigenesis." (PMID 39658878, 2024). "This study identified a mechanism of anti-HER2 resistance and proposed a strategy to overcome it by inhibiting FGFR4 in HER2-positive breast cancer." (PMID 39664391, 2024). "To confirm FGFR4 level in breast cancer, we detected FGFR4 expression in 30 paired TNBC samples and adjacent normal samples." (PMID 39658878, 2024). "The overexpression of FGFR4 is observed in breast cancer clones that are resistant to doxorubicin, a common chemotherapy that inhibits DNA relaxation during transcription." (PMID 39796710, 2024). "Here in this study, we found that FGFR4 was upregulated in breast cancer and correlated with poorer outcome." (PMID 39658878, 2024). "And the results showed that high FGFR4 level was correlated with shortened overall survival, distant metastasis‐free survival, and disease‐free survival of breast cancer." (PMID 39658878, 2024). "FGFR2 is considered to be a susceptibility gene for breast cancer, FGFR4 is a driving factor for breast cancer, and FGFR1 overexpression is found in nearly 50% of breast cancer patients." (PMID 37490511, 2023). "In recalcitrant HER2-positive breast cancer, FGFR4 knockdown reduces resistance to anti-HER2 therapy by activating ferroptosis." (PMID 37063421, 2023). "This decrease in the m6A level prevents YTHDC2-mediated degradation of FGFR4 mRNA, thus leading to the accumulation of FGFR4 in resistant breast cancer cells." (PMID 38072908, 2023). "m6A-hypomethylation mediates upregulation of fibroblast growth factor receptor 4 (FGFR4) in anti-HER2 resistant breast cancer." (PMID 37714846, 2023). "Regarding the m6A-ferroptosis axis, METTL14-modified FGFR4 increases anti-HER2 resistance by inhibiting ferroptosis mediated by the β-catenin/TCF4-SLC7A11/FPN1 axis in recalcitrant HER2-positive breast cancer." (PMID 37063421, 2023). "Overexpression of FGFR4 also occurs in gastric cancer, colorectal cancer, breast cancer, thyroid cancer, and nasopharyngeal carcinoma." (PMID 37750089, 2023). "To elucidate how FGFR4 confers anti-HER2 resistance in breast cancer, we performed RNA next-generation sequencing in FGFR4-suppressed and control rSKBR3 cells." (PMID 35562334, 2022). "FGFR4 expression was detected in 332 cases of HER2-positive breast cancer receiving adjuvant anti-HER2 treatment in the SYSUCC cohort." (PMID 35562334, 2022). "FGFR4 gene amplification has been found in only 2.3% of breast cancer patients, but another study has revealed the presence of FGFR4 mRNA transcript in 30% of patients, particularly in metastasis." (PMID 35193394, 2022). "The results revealed that the WNT signaling pathway was an important downstream target of FGFR4 signaling in resistant HER2-positive breast cancer cells." (PMID 35562334, 2022). "To explore the effect of FGFR4 in driving anti-HER2 resistance, we established FGFR4 overexpression models in anti-HER2 sensitive breast cancer cells." (PMID 35562334, 2022). "Here the authors identify FGFR4 as one of the vulnerabilities of anti-HER2 resistant breast cancer and show that FGRR4 inhibition enhances sensitivity to anti-HER2 treatment in these resistant cells by triggering ferroptosis." (PMID 35562334, 2022). "We found that FGFR4 reduced the sensitivity of HER2-positive breast cancer to trastuzumab plus pertuzumab or tucatinib." (PMID 35562334, 2022).
breast cancer (continued). "Western blot assays revealed that WNT/β-catenin signaling was attenuated after increasing the m6A-modificated level of FGFR4 mRNA in rSKBR3 breast cancer cells." (PMID 35562334, 2022). "Upon evaluation by IHC staining, metastatic tumors had higher FGFR4 expression than primary breast cancers, especially in brain metastases." (PMID 35562334, 2022). "Together, these results pinpoint a mechanism of anti-HER2 resistance and provide a strategy for overcoming resistance via FGFR4 inhibition in recalcitrant HER2-positive breast cancer." (PMID 35562334, 2022). "In conclusion, our study illustrates that FGFR4 confers anti-HER2 resistance by attenuating ferroptosis in breast cancer." (PMID 35562334, 2022). "Although the primary role of FGFR4 in metabolism occurs in hepatocytes, its ablation results in a net inhibitory effect on mammary tumour progression, most likely due to suppressing signals triggered by FGF21 from breast adipocytes." (PMID 35193394, 2022). "Knockdown of METTL14 significantly increased the expression level of FGFR4 in HER2-positive breast cancer cells." (PMID 35562334, 2022). "The antitumor efficacy of the FGFR4 inhibitor roblitinib was further validated in both intrinsic and acquired trastuzumab-resistant breast cancer models." (PMID 35562334, 2022). "Experiments involving patient-derived xenografts and organoids reveals a synergistic effect of anti-FGFR4 with anti-HER2 therapy in breast cancer with either intrinsic or acquired resistance." (PMID 35562334, 2022). "Compared to primary breast cancers, metastatic tumors showed higher FGFR4 expression, especially brain metastases of breast cancer." (PMID 35562334, 2022). "To verify the expression level of FGFR4 in advanced breast cancer, we collected specimens from different sites of recurrence or metastasis." (PMID 35562334, 2022). "Hepatocellular carcinoma, colon cancer, pancreatic cancer, and breast cancer patients have all been found to have FGFR4 activation." (PMID 36147913, 2022). "According to the TCGA and METABRIC databases, FGFR4 mRNA was highly overexpressed in HER2-positive breast cancer." (PMID 35562334, 2022). "FGFR4 amplification occurred in 30 (1.6%) and 13 (1.3%) breast cancer patients in the METABRIC and TCGA datasets, respectively, and was observed in all subtypes, except normal." (PMID 34344433, 2021). "This work highlights how patient-derived models of human breast cancer provide powerful platforms for therapeutic target identification and analysis of drug action, and also the potential of specific FGFRs, including FGFR4, as targets for precision treatment." (PMID 34344433, 2021). "According to previous studies, the FGF19/FGFR4 axis played a pivotal role in many different cancers such as hepatocellular carcinoma, breast cancer, ovarian cancer, and prostate cancer, which led to their low 5-year survival rates." (PMID 34576070, 2021). "In breast cancer patients, FGFR4 and FGFR2 SNPs were previously suggested to be candidate pharmacogenomic factors to predict the response to chemotherapy." (PMID 34830836, 2021). "This provides further evidence that targetable FGFR fusions do occur in breast cancer, albeit at low frequency, and adds further weight to emerging evidence highlighting FGFR4 as a potential therapeutic target in this malignancy." (PMID 34344433, 2021). "Genetic aberrations in FGFR4 are prevalent among various types of cancer like breast cancer, pancreatic cancer, and especially hepatocellular carcinoma (HCC), and these aberrations are associated with poor prognoses." (PMID 33981224, 2021). "The FGFR4 expression levels also seem to be significantly increased in doxorubicin-resistant breast cancer clones." (PMID 32710281, 2020).
breast cancer (continued). "Moreover, a single-nucleotide polymorphism (SNP) in exon 9 of the gene encoding FGFR4 results in the substitution of glycine for arginine at codon 388 (388 Gly/Arg) in the transmembrane domain and is associated with poor outcome in high-grade soft tissue sarcoma, lung, and breast cancers." (PMID 33066597, 2020). "Treatment of high-expressing FGF19 or FGFR4 positive breast cancer cells with an antibody against FGF19 or siRNA to FGF19 sensitizes the cells to doxorubicin." (PMID 32154250, 2020). "Certain genetic variants, such as FGFR4 rs1966265 and FGFR2 rs2981578, have also been involved in the outcome of breast cancer patients treated with chemotherapeutic agents." (PMID 33081025, 2020). "PD173074 is known to be a selective inhibitor of FGFR1, but can block breast cancer cell proliferation via the FGFR4 signaling pathway." (PMID 32555680, 2020). "Yet, increased FGFR4 mRNA levels have been found in up to 30% of breast cancer patients; thus, new investigations are warranted in order to better assess such discrepancy occurring between the amplification of FGFR4 and its mRNA levels." (PMID 33081025, 2020). "Here, we show that in FGFR4+/HER2+ breast cancer cells, particularly under tumor-mimicking 3D conditions, FGFR4 depletion-induced MST1/2 autophosphorylation coupled with MST1 cleavage and nuclear localization without additional stimuli." (PMID 30903103, 2019). "In endogenous FGFR4+/HER2+ breast cancer cell model, this inhibition was essential to counteract apoptosis induction." (PMID 30903103, 2019). "Altogether, our results establish a unique oncogenic signaling mechanism—the dominant FGFR4-mediated attenuation of MST1/2-mediated, stress-associated apoptosis in HER2+ breast cancer cells." (PMID 30903103, 2019). "In breast cancers, FGFR4 is overexpressed in especially ERBB2/HER2-enriched tumors, where it has been linked to tumor growth and apoptosis resistance." (PMID 30903103, 2019). "To consider the overall impact of FGFR4 in human breast cancer, we systematically analyzed (phospho)protein alterations in FGFR4-overexpressing human tumors using TCGA reverse phase protein array (RPPA) data." (PMID 30903103, 2019). "Amplifications of FGFR2 and FGFR4 are rarer, observed in less than 1 and 2.3% of breast cancer patients, respectively." (PMID 31142340, 2019). "Although YAP (pS127 and total) was decreased in FGFR4-overexpressing breast cancers (TCGA RPPA), the FGFR4-dependent and -independent modulation of MST1/2 had variable effects on YAP S127 phosphorylation or localization." (PMID 30903103, 2019). "Another activating point mutation in FGFR4 gene (Y367C) inducing constitutive FGFR4 dimerization, has been found in MDA-MB-453 breast cancer cells." (PMID 30634399, 2019). "In TCGA cohort, FGFR4 overexpression correlated with abysmal HER2+ breast carcinoma patient outcome." (PMID 30903103, 2019). "FGFR4 is highly expressed in a subset of breast cancer cells and primary tumors, suggesting the pivotal role in cell survival via activation of PI3K/AKT." (PMID 30359238, 2018). "The major finding was a significant association of FGFR4 rs1966265 AA genotype and A allele and FGFR2 rs2981578 A alleles with an increased chemosensitivity in NCT of breast cancer patients." (PMID 30359238, 2018). "For example, as many as 33% of HCC patients and 32% of breast cancer patients have FGFR4 overexpression." (PMID 27618313, 2016). "In summary, our results demonstrate that the FGFR4/FGF19 autocrine signaling mediates the survival of a subset of basal-like breast cancer cells through activation of PI3K/AKT signaling." (PMID 27192118, 2016). "As such, targeting the FGFR4/FGF19 autocrine loop represents a potential therapeutic strategy for future management of refractory basal-like breast cancers." (PMID 27192118, 2016).
breast cancer (continued). "siRNA-mediated silencing of FGF19 or neutralization of extracellular FGF19 by anti-FGF19 antibody (1A6) decreases AKT phosphorylation, suppresses cancer cell growth and enhances doxorubicin sensitivity only in the FGFR4+/FGF19+ breast cancer cells." (PMID 27192118, 2016). "Real-time qPCR shows that FGFR4 mRNA is highly expressed, approximately 10- to 2000-fold, in all the breast cancer cells tested as compared to MCF10A and HMEC." (PMID 27192118, 2016). "From a functional screen to identify key drivers of basal-like breast cancer cell growth, we identified fibroblast growth factor receptor 4 (FGFR4) as a potential mediator of cell survival." (PMID 27192118, 2016). "Through an unbiased lentiviral shRNA kinome library screen, we identified FGFR4 as a receptor tyrosine kinase that is required for the survival of a subset of basal-like breast cancer cells." (PMID 27192118, 2016). "We next sought to test the potential benefit of targeting FGF19 therapeutically in breast cancer cells that co-express FGFR4 and FGF19." (PMID 27192118, 2016). "Here, we demonstrated that FGFR4 is highly expressed in a subset of breast cancer cells and primary tumors." (PMID 27192118, 2016). "SNP rs2234909 and rs3135848 in FGFR3 and rs1966265 and rs351855 in FGFR4 were successfully genotyped in 747 breast cancer patients and 716 healthy controls using the SNaPshot method." (PMID 26431494, 2015). "Thus the mechanisms underlying the delay of TGFα-driven breast cancer development by the FGFR4 deficit may be related to metabolic activities of FGF21/19 that cause systemic metabolic programming that in turn impacts local metabolic, and therefore, cellular effects such as the decrease in mitoses." (PMID 24279986, 2013). "Although the primary role of FGFR4 in metabolism occurs in hepatocytes, its ablation results in a net inhibitory effect on mammary tumor progression." (PMID 24279986, 2013). "We investigated mechanisms by which the FGFR4 deficit led to the delay in breast cancer progression driven by the overexpression of TGFα." (PMID 24279986, 2013). "In this report, we examined the development of spontaneous breast cancer driven by overexpression of transforming growth factor (TGF)α in the luminal epithelial cells of mouse breast in a genetic background of FGFR4 deficiency." (PMID 24279986, 2013). "Regarding FGFR4, a previous study has shown that it is over-expressed in a significant fraction of HER2+ breast cancer samples and simultaneous inhibition of FGFR4 and ERBB2 using small molecule inhibitors have synergistic anti-proliferative effect." (PMID 22343619, 2012). "High expression of FGFR4 has also been observed in breast cancer, prostate cancer, pancreatic cancer, and renal cell carcinoma." (PMID 19500394, 2009). "High expression of FGFR4 has been described already for breast cancer, pancreatic cancer and renal cell carcinoma." (PMID 16721364, 2006). "Increased levels of FGF10 are observed in ~10% of human breast cancers, and amplification and overexpression of several FGFRs, including FGFR1, FGFR2, and FGFR4, have been observed in breast cancers." (PMID 16933995, 2006). "Additionally, some breast cancers are resistant to doxorubicin due to frequent elevation of FGFR4 expression, which enhances resistance by upregulating anti-apoptotic protein Bcl-xL via the MAPK pathway." (PMID 41328353, 2026). "Besides, FGFR4 drives basal-like breast cancer cell survival through PI3K/AKT activation, with a subset relying on FGF19-mediated autocrine signaling." (PMID 41210688, 2025). "Aberrant FGFR4 activity drives activation of signaling pathways that promote cell proliferation, survival, and invasion, as observed in epithelial cancers such as non-small cell lung cancer, breast cancer, and prostate cancer." (PMID 40393028, 2025).
breast cancer (continued). "Molecular features that distinctly characterize the HER2E subtype in luminal disease were shown to be consistent with the HER2-enriched subtype in HER2-positive disease, including a putative epigenetic mechanism for FGFR4 expression in primary breast cancer tissue as well as in cell lines." (PMID 40044693, 2025). "Moreover, silencing FGFR4 is also found to increase sensitivity to 5-fluorouracil (5-FU) treatment in breast cancers." (PMID 39796710, 2024). "In breast cancer, FGFR4 was found to promote cell survival via activating the PI3K/AKT pathway." (PMID 39658878, 2024). "FGFR4 has been reported to participate in breast cancer metabolism." (PMID 39658878, 2024). "An increase in FGFR4 expression has been observed in doxorubicin-resistant breast cancer patients." (PMID 38540215, 2024). "The overexpression of FGFR4 in breast cancer, which is instrumental in tumor progression, metastasis, and endocrine resistance, could potentially serve as a compelling target for therapeutic intervention." (PMID 39658878, 2024). "Inhibition of FGFR4 could notably suppress tumor progression, suggesting that the strategic targeting of FGFR4 may serve as a potential approach in the treatment of breast cancer." (PMID 39658878, 2024). "Besides, we further confirmed the prognostic value of FGFR4 in breast cancer with the pan‐BRCA cohorts from bc‐GenExMiner database." (PMID 39658878, 2024). "There are only a few researches about FGFR4 in breast cancer so far." (PMID 39658878, 2024). "FGFR4 was found to be upregulated in breast cancer and correlated with poorer patient outcomes." (PMID 39658878, 2024). "Moreover, the FGF19/FGFR4 axis is suggested to play a critical role in treatment resistance in breast cancer." (PMID 39796710, 2024). "Via sponging miR‐491‐5p, hsa_circRNA‐0001361 could up‐regulate FGFR4 expression level, leading to tumor progression in breast cancer." (PMID 39658878, 2024). "On the other hand, FGFR4 gene amplification is detected in only 2.3% of all breast cancers." (PMID 37296801, 2023). "FGFR4 regulates tumor subtype differentiation and induces metastatic disease in breast cancer." (PMID 36581992, 2022). "Thus, this study pinpoints a mechanism of anti-HER2 resistance and provides a strategy for overcoming this resistance by inhibiting FGFR4 in HER2-positive breast cancer." (PMID 35562334, 2022). "Together, these findings indicated that FGFR4 inhibition could restore sensitivity to anti-HER2 in resistant breast cancer cells." (PMID 35562334, 2022). "The combination of anti-HER2 and anti-FGFR4 might be a broadly effective therapy against both intrinsic and acquired resistant breast cancer." (PMID 35562334, 2022). "Furthermore, FGFR4 has been identified as a critical modulator of enhanced glucose metabolism in breast cancer cells, where high levels of FGFR4 not only increase glucose metabolism but also lead to chemoresistance." (PMID 35193394, 2022). "Earlier studies demonstrated that FGFR4 overexpression may be a result of gene amplification, especially in breast cancer tumors with high lymph node metastases, as well as in estrogen receptor- and progesterone receptor-positive tumors." (PMID 36142417, 2022). "Additionally, FGFR4 was identified as key factor inducing proliferation, metastatic disease, and cell dedifferentiation in aggressive luminal A-like breast cancer." (PMID 35484633, 2022). "A recent study found that breast cancer cell lines can express FGFR4 to gain the ability to resist apoptosis when treated with cyclophosphamide and doxorubicin, while this capacity disappears when the FGFR4 gene is silenced." (PMID 33981224, 2021). "Collectively, this work indicates that FGFR4 inhibitors may have significant impact in management of advanced, endocrine-resistant luminal breast cancer." (PMID 34344433, 2021).